SEC14L2 (SEC14 like lipid binding 2)
Description:
Carrier protein. Binds to some hydrophobic molecules and promotes their transfer between the different cellular sites. Binds with high affinity to alpha-tocopherol. Also binds with a weaker affinity to other tocopherols and to tocotrienols. May have a transcriptional activatory activity via its association with alpha-tocopherol. Probably recognizes and binds some squalene structure, suggesting that it may regulate cholesterol biosynthesis by increasing the transfer of squalene to a metabolic active pool in the cell.
Synonyms: TAP; SPF; C22orf6; KIAA1186; KIAA1658; TAP1
Tractability: Small molecule: a structure with a bound ligand is known; it has a binding pocket of medium quality. PROTAC: ubiquitination databases record sites on it; its protein half-life has been measured.
Gene: Protein-coding gene on chromosome 22 (30,396,941 to 30,425,303, forward strand). Ensembl gene ENSG00000100003.
Subcellular location: Cytoplasm; Nucleus
Subcellular location (Human Protein Atlas): Nucleoplasm; Cytosol
Gene Ontology:
Molecular function: phospholipid binding; vitamin E binding
Biological process: positive regulation of DNA-templated transcription; regulation of cholesterol biosynthetic process
Cellular component: cytosol; extracellular exosome; nucleoplasm; cytoplasm; nucleus
Genetic constraint (gnomAD): Loss-of-function variants: 50 observed, 59.32 expected, observed/expected ratio (o/e) 0.84, 90% interval 0.67 to 1.07. The upper end of that interval is the gene's LOEUF score, 1.07, which puts it in group 4 of 6, group 1 being the genes least tolerant of losing a copy. Missense variants: 414 observed, 520.74 expected, observed/expected ratio (o/e) 0.8, 90% interval 0.73 to 0.86. Synonymous variants: 179 observed, 195 expected, observed/expected ratio (o/e) 0.92, 90% interval 0.81 to 1.04.
Homologues: Orthologues: chimpanzee SEC14L2 (99% identical), macaque SEC14L2 (95% identical), guinea pig SEC14L2 (95% identical), rat Sec14l2 (94% identical), mouse Sec14l2 (93% identical), pig SEC14L2 (89% identical), dog SEC14L2 (86% identical), tropical clawed frog sec14l3 (74% identical), rabbit SEC14L2 (66% identical), zebrafish sec14l7 (62% identical), Drosophila melanogaster CG13893 (30% identical), Caenorhabditis elegans T23G5.2 (29% identical), and 4 more. Paralogues in human: SEC14L3 (77% identical), SEC14L4 (70% identical), SEC14L6 (66% identical), SEC14L5 (33% identical), SEC14L1 (33% identical), TTPA (17% identical).
Diseases named in the same sentence as SEC14L2 in open-access papers:
SEC14L2 is named in the same sentence as 20 diseases in open-access papers, as found by Europe PMC text mining. Sharing a sentence is not in itself a finding about the gene and the disease. The quoted sentences say what the papers report.
hepatoma (7 papers, 2017 to 2026). "In hepatocellular carcinoma (HCC), expression of SEC14L2 is associated with the effect of antiviral drugs on hepatocytes and, in some cases, can enhance the therapeutic effect of the drugs." (PMID 41585138, 2026). "The expression of host factor, SEC14L2 (SEC14-like protein 2) enabled replication of pan HCV genotypes in hepatoma cell lines." (PMID 38739590, 2024). "Modification of the innate immune-sensing pathways of Huh7.5 hepatoma cells by expression of the parainfluenza virus type 5 V protein and SEC14L2 resulted in a further enhancement of S52 replication." (PMID 28984238, 2017). "We also investigated the expression of SEC14L2, a recently identified intracellular factor that enables RNA replication of diverse HCV genotypes in hepatoma cell lines." (PMID 29538454, 2018). "Notably, SEC14L2 expression could not be detected in human hepatoma and non-hepatoma cell lines in vitro." (PMID 31851620, 2019).
breast carcinoma (4 papers, 2010 to 2019). "For example, no study has so far implicated SEC14L2 in liver cancer, though proteomic analysis identified low levels of SEC14L2 to be prognostic markers for overall breast cancer survival." (PMID 31851620, 2019). "Several of these genes have been linked to breast cancer (MAPT, HMGCS2, NR2F2, TFAP2B, NTN4, SEC14L2 and LTF)." (PMID 21209903, 2010). "Reduced expression of SEC14L2 has been reported in human breast cancer, indicating that SEC14L2 may serve as a tumor suppressor." (PMID 27175595, 2016). "Among the listed genes, BIRC5, SEC14L2, Thymidine kinase (TK1), ZNF385B, CLIC6, ELOVL1, CHAF1B and TFF1 have been reported to have a role in early detection of cancers, tumor progression and metastasis in most of cancer types including breast cancer." (PMID 31703592, 2019).
liver cancer (2 papers, 2019 to 2021). An epithelial or non-epithelial malignant neoplasm that arises from the liver. "Further validation showed that the expression of SEC14L2 and SLC6A in 371 liver cancers was lower than that in 50 paracancer samples; 50 samples were paired to explain the expression of the genes in cancer and paracancer tissues." (PMID 34141458, 2021).
atherosclerosis (1 paper, 2025). A disease characterized by the build-up of fatty material and calcium deposition in the arterial wall resulting in partial or complete occlusion of the arterial lumen. "If this variant causes a SEC14L2 gain-of-function, it can boost cholesterol synthesis, accelerate atherosclerosis, and raise intraocular pressure, leading to glaucoma and impaired lens microcirculation." (PMID 40649110, 2025).
bladder urothelial carcinoma (1 paper, 2021). "The expression of SEC14L2 was significantly lower in some cancers, including bladder urothelial carcinoma, cholangiocarcinoma, kidney chromophobe, lung adenocarcinoma, and HCC." (PMID 34141458, 2021).
breast tumors (1 paper, 2022). "A previous study demonstrated that TAP was downregulated in breast cancer; therefore, TAP/SEC14L2 may function as a tumor suppressor in breast tumors." (PMID 35281270, 2022).
glaucoma (1 paper, 2025). Increased pressure in the eyeball due to obstruction of the outflow of aqueous humor. "People with a SEC14L2-encoding gene variant have a higher glaucoma risk." (PMID 40649110, 2025).
glioblastoma (1 paper, 2016). The most malignant astrocytic tumor (WHO grade IV). "For these reasons, binding of SEC14L2 to tocopherol and other interaction partners might be impaired in glioblastoma cases." (PMID 27175595, 2016). "In addition to its tocopherol binding mechanism, SEC14L2 binds phosphatidylinositol and is implicated in the regulation of the phosphatidylinositol 3-kinase/AKT signaling pathway, a pathway frequently disturbed in glioblastoma." (PMID 27175595, 2016).
prostate carcinoma (1 paper, 2021). A carcinoma that arises from epithelial cells of the prostate gland. "Previous studies demonstrated that low expression of TAP (protein encoded by SEC14L2) was associated with higher Ki-67 expression in prostate cancer tissue." (PMID 33758595, 2021).
tumor (10 papers, 2016 to 2026). "The decreased CD24 mRNA expression induced by Doxy treatment in tumor grafts was also associated with the decreased SEC14L2 expression." (PMID 41585138, 2026). "Upregulation of SEC14L2 was associated with advanced tumor stage, grade, and metastasis in cancer patients." (PMID 41585138, 2026). "Taken together, these results implicated the potential tumor suppressive role of SEC14L2 in CRPC." (PMID 33758595, 2021). "SEC14L2 was highly upregulated in TCGA HNSCC tumor cohorts and our OSCC tumor cohorts compared to normal controls." (PMID 41585138, 2026). "We found significant methylation of SEC14L2 in various clinical factors, including new tumor events after initial treatment, histological type, gender, tumor stage, and OS." (PMID 34141458, 2021). "Periodic volume measurements showed that tumor growth was nearly abolished after SEC14L2-transduction, compared with tumors containing control cells." (PMID 31851620, 2019). "Besides, the neo-antigenic SEC14L2 peptide identified from the breast cancer mediated the anti-tumor T cell functions." (PMID 41585138, 2026). "One novel MR, SEC14L2, exerted an anti-proliferative effect in HCC cells and strongly suppressed tumor growth in a mouse model." (PMID 31851620, 2019). "Further support for the importance of SEC14L2 comes from our functional in vivo experiment, indicating that restoration of SEC14L2 expression in HCC cells significantly inhibited tumor growth." (PMID 31851620, 2019). "In the TCGA_LIHC cohort, 16 of 120 genes were downregulated in HCC tissue rather than in adjacent non-tumor tissue, and 9 of 16 genes, namely, ALDH8A1, C11orf96, CLYBL, EFNB3, ENG, NPC1L1, PIM3, SEC14L2, and SLC8A1, displayed a significant difference (p < 0.05)." (PMID 33352935, 2020).
cancer (5 papers, 2019 to 2026). A tumor composed of atypical neoplastic, often pleomorphic cells that invade other tissues. "SEC14L2 can regulate lipid metabolic pathways and inhibit the growth and proliferation of cancer cells." (PMID 41585138, 2026).
infection (4 papers, 2016 to 2024). The state of being infected such as from the introduction of a foreign agent such as serum, vaccine, antigenic substance or organism. "Upon entering the imHC cells, HCV virions were protected from lipid peroxidation through increasing SEC14L2 expression via vitamin E treatment during infection." (PMID 38739590, 2024). "The expression of SEC14L2 increased to 1.60 folds on 3 dpi and reversed to 0.65 folds on 14 dpi after clinical isolate infection." (PMID 38739590, 2024). "Together with the expression of SEC14L2 and the addition of α-tocopherol, the HCVser infection in HLCs were further intensified." (PMID 27044429, 2016). "In the case of GLT1 serum infection, no pronounced additive effect of the combination of PCi treatment and SEC14L2 overexpression in comparison to PCi treatment alone could be detected when comparing our results to the results of a previous study." (PMID 39772180, 2024).
SEC14L2 also shares sentences with these, for which no sentence is quoted: anemia (1 paper); astroblastoma (1); cholangiocarcinoma (1); Infertility (1); lung adenocarcinoma (1); malaria (1); oral squamous cell carcinomas (1); virus infection (1).